H19 (H19 imprinted maternally expressed transcript)
Diseases named in the same sentence as H19 in open-access papers (continued):
Sharing a sentence is not in itself a finding about the gene and the disease.
pulmonary arterial hypertension (15 papers, 2018 to 2025). Pulmonary arterial hypertension (PAH) is a group of diseases characterized by mean pulmonary artery pressure >20 mmHg and elevated pulmonary arterial resistance leading to right heart failure. "Plasma H19 was upregulated in pulmonary artery hypertension patients with decompensated right heart failure." (PMID 35461308, 2022). "Omura used CMs from rats with pulmonary hypertension to demonstrate that H19 silencing upregulates the histone methyltransferases, enhancer of Zeste homolog 2 (EZH2) and E2F1." (PMID 36188624, 2022). "H19 magnifies the proliferation of pulmonary artery smooth muscle cells through AT1R via sponging let-7b in monocrotaline-induced pulmonary arterial hypertension." (PMID 34130625, 2021). "In a study on pulmonary hypertension, melatonin reduced H19 expression and, therefore, also that of miR-675-3p, whereas H19 was shown to suppress miR-200a." (PMID 30862067, 2019). "The best-studied lncRNA in the context of pulmonary hypertension is the H19 lncRNA." (PMID 37461108, 2023). "Notably, H19 has been found to promote the pathogenesis of pulmonary arterial hypertension (PAH), suggesting that it might also contribute to SARS-CoV-2 acute pulmonary injury." (PMID 33670580, 2021). "Observational studies indicate that lncRNA H19, which promotes pulmonary arterial hypertension (PAH), promotes abdominal aortic aneurysm in mice and pigs." (PMID 34830125, 2021). "Similarly, H19 may promote the pathogenesis of pulmonary arterial hypertension (PAH) by targeting let-7b to enhance angiotensin II receptor type 1 (AT1R) expression and smooth muscular cell proliferation." (PMID 32272875, 2020). "LncRNA H19 in plasma was identified to indicate the severity and prognosis of PAH(pulmonary arterial hypertension)." (PMID 32969576, 2020).
renal fibrosis (15 papers, 2016 to 2025). A final common manifestation of a wide variety of chronic kidney diseases characterized by glomerulosclerosis and tubulointerstitial fibrosis. "Using TGF-β-induced HK-2 cells, StarBase 2.0 to identify miRNA recognition sites associated with lncRNA H19 during renal fibrosis, including miR-20, miR-93, miR-106, miR-18, and miR-17." (PMID 37964955, 2023). "Consistent with earlier studies, the H19 gene has been shown to influence the development of renal fibrosis in diabetic mice." (PMID 39898248, 2025). "H19 was found to be upregulated and promote renal fibrosis in mice after unilateral ureteral obstruction." (PMID 34697716, 2022). "Upregulated H19 expression and downregulated miR-17 were confirmed in animal models of renal fibrosis." (PMID 32295041, 2020). "For example, lncRNA Erbb4-IR was found to promote renal fibrosis by targeting miR-29b while other studies demonstrated that inhibition of Linc00963 and H19 were protective against renal fibrosis." (PMID 30914951, 2019). "Collectively, these results indicate that H19 expression is significantly up-regulated during renal fibrosis in vivo and in vitro." (PMID 27391349, 2016). "We also detected up-regulated H19 expression and down-regulated miR-17 expression in the early and advanced animal models of renal fibrosis." (PMID 27391349, 2016). "Targeting the lnRNA H19 has already been tested in renal fibrosis." (PMID 41439975, 2025). "In AKI model mice, the elevated expression of lncRNA H19 has been shown to stimulate the synthesis of Wnt and β-catenin through sponging miR-196a-5p, promoting Wnt/β-catenin signaling pathway, which in turn promotes renal fibrosis." (PMID 37964955, 2023). "Another recent study demonstrated a favorable correlation between lncRNA H19 and renal fibrosis." (PMID 37964955, 2023). "Moreover, Xie showed that lncRNA-H19 expression was significantly upregulated in TGF-β2-induced HK-2 cell fibrosis and unilateral ureteral obstruction (UUO)-induced renal fibrosis in vivo, indicating that H19 upregulation contributes to renal fibrosis." (PMID 33716779, 2021). "H19 knockdown inhibited TGF-β2-induced renal fibrosis in vitro and in vivo." (PMID 27391349, 2016). "We then determine the role of H19 in the development of renal fibrosis in vivo." (PMID 27391349, 2016). "This study indicates that H19 up-regulation contributes to renal fibrosis." (PMID 27391349, 2016). "Once lncRNA-H19 was induced in renal fibrosis, increased H19 levels could alleviate miR-17 repressive effect, and lead to increased expression of fibronectin, a target gene of miR-17." (PMID 27391349, 2016). "H19 knockdown attenuated renal fibrosis through lncRNA-H19/miR-17/fibronectin regulatory network." (PMID 27391349, 2016). "Moreover, up-regulated H19 expression and down-regulated miR-17 expression was detected in the early and advanced animal models of renal fibrosis." (PMID 27391349, 2016). "We next investigated whether H19 knockdown affected the development of renal fibrosis." (PMID 27391349, 2016). "Moreover, we determined H19 expression in a renal fibrosis mouse model of UUO nephropathy." (PMID 27391349, 2016). "Several lncRNAs, such as MEG3, H19 and HOTAIR, were reported to play important roles in mediating TGF-β and renal fibrosis." (PMID 32203053, 2020). "In conclusion, we showed that H19 level was significantly up-regulated in TGF-β2-induced HK-2 cell fibrosis in vitro and unilateral ureteral obstruction (UUO)-induced renal fibrosis in vivo." (PMID 27391349, 2016). "UUO kidney displayed obvious renal fibrosis as shown by increased expression of α-SMA and collagen IV, whereas H19 knockdown reduced the up-regulation of α-SMA and collagen IV expression at gene and protein levels." (PMID 27391349, 2016). "Thus, H19 regulation could alter fibronectin level, which in turn affected renal fibrosis." (PMID 27391349, 2016).
renal fibrosis (continued). "In this study, we investigate the role of H19 in renal fibrosis using TGF-β2-induced renal cell model and mouse model of renal fibrosis." (PMID 27391349, 2016). "Moreover, Xie showed that lncRNA-H19 expression was significantly upregulated in TGF-β2-induced HK-2 cell fibrosis and UUO-induced renal fibrosis in vivo, indicating that H19 upregulation contributes to renal fibrosis." (PMID 33716779, 2021).
hepatoblastoma (14 papers, 2000 to 2024). Hepatoblastoma (HB) is a malignant hepatic tumor and is the most common pediatric liver cancer. "In this case‐control study of 213 patients with hepatoblastoma and 958 healthy controls, we found that rs2839698, rs3024270 and rs217727 H19 polymorphisms are significantly associated with hepatoblastoma susceptibility." (PMID 33236528, 2021). "In this study, we demonstrated the relationship between three H19 SNPs and hepatoblastoma susceptibility: rs2839698 and rs3024270 increased hepatoblastoma risk, whereas rs217727 polymorphism decreased hepatoblastoma risk in a Chinese Han population." (PMID 33236528, 2021). "In this study, we found that lncRNA H19 polymorphisms were significantly associated with hepatoblastoma risk." (PMID 33236528, 2021). "Overall, the H19 rs2839698, rs3024270 and rs217727 polymorphisms were associated with hepatoblastoma susceptibility in a Chinese Han population." (PMID 33236528, 2021). "In this study, we investigated the association between three H19 polymorphisms (rs2839698 G>A, rs3024270 C>G, rs217727 G>A) and hepatoblastoma susceptibility in 213 hepatoblastoma patients." (PMID 33236528, 2021). "The AG genotype reduced the risk of hepatoblastoma compared to the GG genotype (adjusted OR = 0.58, 95% CI = 0.42‐0.80, P = .0009), while H19 rs217727 polymorphism was associated with significantly lower hepatoblastoma risk (dominant model: adjusted OR = 0.58, 95% CI = 0.43‐0.79, P = .0004)." (PMID 33236528, 2021). "Moreover, H19 rs2839698 polymorphism was associated with significantly increased risk of hepatoblastoma (recessive model: adjusted odds ratio (OR) = 1.68, 95% confidence interval (CI) = 1.10‐2.58, P = .017)." (PMID 33236528, 2021). "H19 polymorphisms are associated with increased susceptibility to several cancers; however, their role in hepatoblastoma remains unclear." (PMID 33236528, 2021). "Therefore, we investigated the association between three H19 polymorphisms (rs2839698 G>A, rs3024270 C>G, rs217727 G>A) and hepatoblastoma susceptibility, using the odds ratio and 95% confidence interval to determine the strength of the association." (PMID 33236528, 2021). "The molecular pathways involved in H19-induced apoptosis in hepatoblastoma cells were discovered, and it was found that H19 suppressed the growth of hepatoblastoma cells by promoting apoptosis via the miR-675/FADD and miR-138/PTK2 signaling pathways." (PMID 38355574, 2024). "In HBV-induced hepatoblastoma, H19 was overexpressed and directly targeted miR-675 to regulate FADD, caspase-8, and caspase-3 expression." (PMID 34977037, 2021). "The overexpression of IGF2 and the reduced expression of H19 would play an important role in tumorigenesis of hepatoblastoma." (PMID 24373183, 2013). "Hypermethylation at H19-DMR and hypomethylation at IGF2-DMR0 associated with biallelic expression of IGF2 were reported in adult and embryological tumors, including hepatoblastoma." (PMID 24373183, 2013). "Patterns of allele-specific expression of H19 and insulin-like growth factor-2 (IGF-2) were examined in tissue obtained from 30 children diagnosed with hepatoblastoma." (PMID 10732739, 2000). "In patients with non-BWSp-associated hepatoblastoma, SNPs in the H19 gene have been associated with decreasing or increasing hepatoblastoma risk." (PMID 35804856, 2022). "Further functional studies on these SNPs with larger populations and different ethnicities could verify the role of H19 SNPs in hepatoblastoma." (PMID 33236528, 2021). "Despite increasing evidence suggesting that H19 polymorphisms are associated with increased susceptibility to many cancers, the association between H19 polymorphisms and hepatoblastoma susceptibility has not yet been investigated." (PMID 33236528, 2021). "H19, as an oncogene, inhibited cell apoptosis in hepatoblastoma via both signaling axes." (PMID 34977037, 2021).
hepatoblastoma (continued). "Hepatoblastoma development has been associated with UPD (4.7%, P < 0.001) although it is also observed in patients with KCNQ1OT1:TSS-DMR-LOM (0.7%) and H19/IGF2:IG-DMR -GOM (0.8%, P < 0.001)." (PMID 33101381, 2020). "We show that mosaic 11p15.5 alterations in liver FFPE sections of hepatoblastoma patients display IGF2 overexpression and H19 downregulation together with an alteration of the liver zonation." (PMID 37932266, 2023).
Sepsis (14 papers, 2020 to 2025). Sepsis is defined as life-threatening organ dysfunction caused by a dysregulated host response to infection. "lncRNA H19 alleviates sepsis-induced acute lung injury by downregulating the expression of TNF-α, IL-6, IL-17, caspase-3, caspase-9, and Bax while upregulating Bcl-2 levels, thereby suppressing lung cell apoptosis and inflammation." (PMID 39940682, 2025). "H19 sponged miR-93-5p to promote SORBS2 expression.H19 suppressed sepsis-induced myocardial injury via regulation of the miR-93-5p/SORBS2 axis." (PMID 40041174, 2025). "In sepsis-induced acute lung injury, upregulation of lncRNA H19 inhibited TNF-α, IL-1β, IL-6, IL-10, and BAX to suppress pulmonary apoptosis and inflammation." (PMID 39940682, 2025). "Another study investigated the relationship between AQP1, miRNA-874 and lncRNA H19 in LPS-induced sepsis." (PMID 39544938, 2024). "We found that lncRNA H19 was poorly-expressed in the mouse model and cell model of sepsis-induced ALI, while overexpression of H19 suppressed apoptosis and inflammation in sepsis-induced ALI in vivo and in vitro, in which the miR-107/TGFBR3 axis was involved." (PMID 36180862, 2022). "lncRNA H19 significantly reverses sepsis-induced inflammatory response and myocardial dysfunction through miR-874/AQP1." (PMID 36274974, 2022). "It has previously been observed that H19 is downregulated in mice with LPS-induced sepsis and in sera of sepsis patients." (PMID 36180862, 2022). "Taken together, overexpression of H19 inhibited the production of pro-inflammatory cytokines and apoptosis in sepsis-induced ALI." (PMID 36180862, 2022). "The primary finding in this research was that lncRNA H19 inhibited inflammation in sepsis-induced ALI by regulating the miR-107/TGFBR3 axis." (PMID 36180862, 2022). "Considering that H19 negatively regulates miR-874 expression in LPS sepsis, we searched the downstream miRNAs of H19 and identified miR-107." (PMID 36180862, 2022). "In conclusion, the present study highlighted that lncRNA H19 ameliorated apoptosis and inflammation in sepsis-induced ALI through the miR-107/TGFBR3 axis." (PMID 36180862, 2022). "This study aimed to investigate the mechanism of H19 in alleviating sepsis-induced ALI through the miR-107/TGFBR3 axis." (PMID 36180862, 2022). "A previous report on the role of H19 in protection of the intestinal barrier in sepsis seems to conflict with our results." (PMID 34630738, 2021). "The results of these studies propose that lnRNA H19 could be used as a biomarker of early sepsis diagnosis." (PMID 39768394, 2024). "The authors concluded that H19 expression could serve as a potential therapeutic target for LPS-induced sepsis and myocardial dysfunction." (PMID 39768394, 2024). "H19 acted as a competitive endogenous RNA (ceRNA) for AQP1 by regulating miR-874, reversing LPS-induced inflammatory responses and myocardial dysfunction, suggesting H19 as a potential therapeutic target for sepsis-associated myocardial dysfunction." (PMID 39544938, 2024). "The current study attempted to prove the hypothesis with the expectation to understand the mechanism of H19 in sepsis, offer novel therapeutic targets, and lay a theoretical foundation for the treatment of sepsis." (PMID 36180862, 2022). "One major drawback of the study is the lack of sufficient investigation into the regulatory mechanism of lncRNA H19 in inflammation in sepsis-induced ALI, for example, through modulating several signaling pathways downstream of TGFBR3, which we plan to include in future studies." (PMID 36180862, 2022). "Additionally, existing research recognizes the correlation between H19 and inflammatory reaction and oxidative stress in rats with sepsis-triggered ALI." (PMID 36180862, 2022). "H19 plays a regulatory role in sepsis through the ceRNA mechanism." (PMID 36180862, 2022). "Furthermore, we explored the downstream regulatory mechanism of the H19/miR-107 axis in sepsis-induced ALI." (PMID 36180862, 2022).
Sepsis (continued). "Meanwhile, H19 is recognized as an inhibitory factor of sepsis-induced kidney injury and ALI." (PMID 36180862, 2022). "Up-regulation of H19 suppressed inflammatory responses in sepsis-induced myocardial injury." (PMID 34956235, 2021). "A prior study found that H19 had anti-inflammatory properties and illustrated that H19 was inhibited in sepsis patients and that the H19 overexpression might have a reversal effect on the LPS-induced myocardial dysfunction and production of anti-inflammatory cytokines both in vitro and in vivo." (PMID 36787444, 2023). "Hence, we hypothesized that lncRNA H19 limited inflammatory responses in sepsis-induced ALI through the miR-107/TGFBR3 axis." (PMID 36180862, 2022). "It was found that H19 and AQP1 expressions decreased while miR-874 expression increased in sepsis samples, mouse models and cardiomyocytes." (PMID 39544938, 2024). "In another study, reduced H19 and AQP1 expression, coupled with increased miR-874 levels, were observed in sepsis patients, a lipopolysaccharide (LPS)-treated mouse model and in cell culture." (PMID 39544938, 2024). "H19 overexpression reduced total protein concentration and the number of total cells, neutrophils, and macrophages in BALF of mice with sepsis-induced ALI." (PMID 36180862, 2022). "Several reports have shown that lncRNA H19 is capable of protecting against both ALI and sepsis." (PMID 36180862, 2022). "As mentioned in the literature, lncRNA H19 is downregulated in the CLP mouse model and cell model of LPS-stimulated cell injury, while upregulation of H19 can ameliorate lung injury in mice with sepsis." (PMID 36180862, 2022). "H19, SNHG16, and NEAT1 are also involved in sepsis progress." (PMID 33204219, 2020). "Given the previous report of H19 acting as an hsa-miR-301a-3p sponge to mitigate lung injury in sepsis models and the positive correlation we observed between H19 and GAS1 in RIF, we hypothesize that H19 may serve as a ceRNA, regulating GAS1 expression by competitively binding to hsa-miR-301a-3p." (PMID 38968269, 2024). "However, the previous studies of lncRNA H19 have not dealt with the action and concrete mechanism of H19 in sepsis-evoked ALI." (PMID 36180862, 2022). "Subsequently, an in vitro model of sepsis-induced ALI was established using LPS-induced PMVECs, and H19 was overexpressed in LPS-induced PMVECs via transfection to explore the specific in vitro mechanism of H19 in cell apoptosis and secretion of inflammatory cytokines." (PMID 36180862, 2022).